S100A10 (S100 calcium binding protein A10)
Description:
Because S100A10 induces the dimerization of ANXA2/p36, it may function as a regulator of protein phosphorylation in that the ANXA2 monomer is the preferred target (in vitro) of tyrosine-specific kinase.
Synonyms: ANX2LG; CAL1L; CLP11; P11; 42C; ANX2L; Ca[1]; GP11; p10
Tractability: Antibody: its Gene Ontology location is reachable by antibodies, with high confidence. PROTAC: UniProt records ubiquitination sites on it; ubiquitination databases record sites on it; its protein half-life has been measured; a small molecule that binds it is known.
Gene: Protein-coding gene on chromosome 1 (151,982,903 to 151,993,859, reverse strand). Ensembl gene ENSG00000197747.
Subcellular location (Human Protein Atlas): Mitochondria
Pathways (Reactome):
Hemostasis: Dissolution of Fibrin Clot
Gene Ontology:
Molecular function: lipid binding; protein binding; protein homodimerization activity; transmembrane transporter binding; calcium ion binding; calcium-dependent protein binding
Biological process: membrane raft assembly; positive regulation of focal adhesion assembly; positive regulation of GTPase activity; positive regulation of plasminogen activation; positive regulation of stress fiber assembly; positive regulation of substrate adhesion-dependent cell spreading; protein localization to plasma membrane; vesicle budding from membrane; positive regulation of exocytosis; positive regulation of plasma membrane repair; mRNA transcription by RNA polymerase II; positive regulation of transcription by RNA polymerase II; regulation of neurogenesis
Cellular component: AnxA2-p11 complex; extracellular exosome; extracellular matrix; extracellular region; membrane raft; plasma membrane; plasma membrane protein complex; RNA polymerase II transcription regulator complex; cytoplasm; nuclear matrix; cell surface
Genetic constraint (gnomAD): Loss-of-function variants: 1 observed, 4.35 expected, observed/expected ratio (o/e) 0.23, 90% interval 0.081 to 1.08. That is too few expected variants to judge how well the gene tolerates losing a copy. Missense variants: 73 observed, 85.52 expected, observed/expected ratio (o/e) 0.85, 90% interval 0.71 to 1.04. Synonymous variants: 30 observed, 29.32 expected, observed/expected ratio (o/e) 1.02, 90% interval 0.76 to 1.39.
Homologues: Orthologues: chimpanzee S100A10 (100% identical), macaque S100A10 (100% identical), pig S100A10 (100% identical), rabbit S100A10 (100% identical), mouse S100a10 (92% identical), rat S100a10 (89% identical), tropical clawed frog s100a10 (61% identical), zebrafish s100t (42% identical). Paralogues in human: S100A1 (44% identical), S100Z (41% identical), S100P (39% identical), S100A11 (38% identical), S100A4 (36% identical), S100B (35% identical), S100A2 (33% identical), S100A5 (31% identical), S100A9 (30% identical), S100A13 (29% identical), S100A12 (28% identical), S100A7A (27% identical), and 9 more.
Diseases named in the same sentence as S100A10 in open-access papers:
S100A10 is named in the same sentence as 157 diseases in open-access papers, as found by Europe PMC text mining. Sharing a sentence is not in itself a finding about the gene and the disease. The quoted sentences say what the papers report.
breast carcinoma (33 papers, 2013 to 2025). "In the MMTV-PyMT transgenic mammary tumor model, loss of S100A10 resulted in a significant decrease in spontaneous pulmonary metastatic burden." (PMID 41463352, 2025). "The abnormal expression of S100A10 was associated with drug resistance in multiple cancer types including colorectal cancer, neuroblastoma, breast cancer, and ovarian cancer." (PMID 36430822, 2022). "The knockdown of annexin A2 and concurrent loss of S100A10 expression decreases the cell proliferation of invasive MDA-MB-435S breast cancer cells." (PMID 30572596, 2018). "Increased S100A10 has been associated with tamoxifen resistance in MCF-7 breast cancer cells and breast cancer tissues." (PMID 30572596, 2018). "Increased cell proliferation of basal-type breast cancer cells is associated with upregulation of S100A10 expression." (PMID 30572596, 2018). "S100A10 and S100Z mRNA expression were associated with lower OS in basal-like breast cancer." (PMID 28051137, 2017). "Under cytotoxic chemotherapy, breast cancer stem cells (BCSCs) respond to chemotherapy-induced hypoxia inducible factor-1 (HIF-1)-dependent S100A10 expression." (PMID 40234383, 2025). "In breast cancer, elevated S100A10 corresponds to lung metastasis, especially the aggressive triple-negative subtype, as supported by both human data and S100A10-deficient mouse models." (PMID 41164170, 2025). "S100A10 acts as a metastasis‐promoting factor by encouraging invasiveness in breast cancer stem cells." (PMID 40384436, 2025). "S100A10 overexpression, which occurs in many cancers, including breast cancers, enhances tumor cell invasion, migration, and metastasis through increased ECM degradation." (PMID 41463352, 2025). "Yanagi et al22 found that S100A10 acts as a promoter of breast cancer stem cells, thereby increasing the invasion ability of breast cancer." (PMID 39128058, 2024). "S100A10 upregulation after chemotherapy treatment has been observed in colorectal cancer, leukemia, ovarian cancer, breast cancer, and neuroblastoma." (PMID 37892132, 2023). "Silencing ANXA2 was shown to downregulate S100A10 and to inhibit breast cancer proliferation and invasion." (PMID 35631574, 2022). "Our laboratory recently performed a comprehensive analysis of S100A10 mRNA and protein expression using gene expression profiling and immunohistochemical (IHC) staining using two different cohorts of breast cancer tissues from Canada." (PMID 34944416, 2021). "The cancer-promoting effect of S100A10 is obvious in ovarian cancer, the protein also stimulates production of breast cancer stem cells." (PMID 34148033, 2021). "The role of S100A10 in metastasis has also been examined using a breast cancer patient-derived tumor xenograft (PDX) mouse model." (PMID 34944416, 2021). "Comprehensive studies describing the expression of S100A10 in breast cancer are by far few and limited." (PMID 34944416, 2021). "There is evidence that S100A10 has potential value as a biomarker that represents the high-grade cell state of breast cancer." (PMID 34530774, 2021). "In summary, S100A10 has a tremendous potential to be employed as a biomarker, especially for predicting high-grade breast cancer." (PMID 34944416, 2021). "This study illustrates how breast cancer cells that have left the tumor and invaded into the blood require only to upregulate a single plasminogen receptor, namely S100A10." (PMID 34944416, 2021). "Using in silico analysis of 1247 human breast cancer specimens in the Cancer Genome Atlas database, they reported that S100A10 expression was regulated by HIF in most human breast cancers." (PMID 34944416, 2021). "As a S100 protein, S100A10 has increased expressions in breast cancer, lung cancer, gastric cancer, and pancreatic ductal cancer." (PMID 34178044, 2021). "To date, the few studies that have reported the expression of S100A10 in breast cancer predominantly use gene expression profiling and present contrasting evidence/findings." (PMID 34944416, 2021).
breast carcinoma (continued). "Our work, therefore, was consistent with other studies showing the importance of S100A10 in breast cancer." (PMID 34944416, 2021). "Numerous studies have confirmed that S100A10 is an oncogene, such as intestinal cancer, basal-type breast cancer, lung cancer, ovarian cancer, pancreatic ductal cancer, and gastric cancer." (PMID 34178044, 2021). "Compared to normal tissues, S100A10 was overexpressed in bladder cancer, brain cancer, breast cancer, GC, head and neck cancer, kidney cancer, leukemia, liver cancer, lymphoma, myeloma, pancreatic cancer, and prostate cancer." (PMID 33324631, 2020). "We employed a well-defined breast cancer patient cohort (n = 176) and stratified the patient population into S100A10 high and low mRNA levels." (PMID 33297495, 2020). "Myrvang and coworkers (2013) were able to show that cell surface S100A10 promotes the adhesion of breast cancer cells to endothelial cells in vitro." (PMID 30572596, 2018). "Interestingly, we also observed that the breast cancer cell line MDA MB 231 that expresses oncogenic KRAS (which is not a commonly acquired mutation in this type of cancer) shows higher levels of expression of S100A10 compared to the breast cancer cell line MCF7 that express WT KRAS." (PMID 27351226, 2016). "S100A10 has been reported as the 3′-partner gene in the HDGF/S100A10 fusion gene which was found in the UACC-812 breast cancer cell line." (PMID 24604026, 2014). "Furthermore, upon isolating macrophages and Ly6g+ neutrophils from lungs with 4T1 breast cancer metastasis, we found that macrophages expressed higher levels of ApoE, S100A10, and S100A4 than those macrophages isolated from normal mice." (PMID 39695088, 2024). "In addition, higher S100A10 expression is also reported to be correlated with shorter survival rates in gastric cancer and breast cancer." (PMID 36612197, 2022). "Specifically, S100A10 in a heterotetramer with Annexin II can act as co-receptor for tPA, plasminogen and pro-cathepsin B to promote invasion and metastasis in breast carcinoma and glioma cells, but it can also affect macrophage invasion and breast cancer cell proliferation." (PMID 33809973, 2021). "Gene expression profiling of a 176, well-defined breast cancer patient cohort from the Canadian Breast Cancer Foundation suggested a consistent relationship between S100A10 gene and protein expression and correlation between histological, pathological, and molecular subtypes of breast cancer." (PMID 34944416, 2021). "Moreover, S100A10 was significantly increased in high-grade compared to low-grade breast cancer, and ER-negative breast cancer showed increased expression of S100A10 compared to ER-positive cancer." (PMID 34944416, 2021). "Next, we established the MMTV-PyMT (mouse mammary tumor virus-polyoma middle tumor-antigen) transgenic breast cancer model in wild-type and S100A10 knockout mice and used this double transgenic model to investigate the role of S100A10 in breast cancer malignancy." (PMID 34944416, 2021). "The expression of S100A10 is also upregulated in basal-type breast cancers." (PMID 30572596, 2018). "Interestingly, this group reported the activation of the S100A10 gene during intravasation of breast cancer cells and showed that S100A10 was one of only 170 genes activated during this process." (PMID 27351226, 2016). "Conserved expression of markers such as S100A10 indicates metastatic potential, paralleling known biology of disease aggressiveness within HER2 expressing breast cancer." (PMID 36598637, 2023). "Our laboratory has contributed to understanding the function of S100A10 in the pathogenesis of pro-myelocytic leukemia (PML), pancreatic cancer, and breast cancer." (PMID 37892132, 2023). "In the breast cancer cell line MCF7, P4 elicits changes in the expression of S100A11, S100A10, calreticulin, VDAC1, SERCA3, and SERCA1, resulting in a barely Ca2+ efflux from the endoplasmic reticulum as well as impaired membrane potential in the mitochondria." (PMID 33076541, 2020).
breast carcinoma (continued). "In fact, annexin A2 mediates tPA-dependent plasmin generation (probably through S100A10) and promotes the in vitro migration of MDA-MB-231 breast cancer cells." (PMID 23519104, 2013). "This machinery is anticipated to work cooperatively with integrin-β1; however, S100A10 is not drastically elevated compared to normal tissues in invasive breast cancer tissue specimens." (PMID 38595825, 2024). "Although some reports also evidenced that S100A10 participated in the development of ovarian cancer, breast cancer, and gastric cancer via different pathways, the mechanism for the function of S100A10 has not been clarified." (PMID 37420211, 2023). "The earliest study of S100A10 expression in breast cancer using serial analysis of gene expression (SAGE) identified that S100A10 was downregulated in breast cancer tissue irrespective of pathological grade." (PMID 34944416, 2021). "For example, we observed that the oncogenic KRAS expressing breast cancer cell line MDA MB 231 showed much higher levels of S100A10 compared to MCF7 breast cancer cells (that do not express oncogenic RAS)." (PMID 27351226, 2016). "However, the S100A10 expression level was not highly noticeable in the invasive breast cancers in our in silico analysis; rather S100A11, S100A14, and S100P were markedly elevated in the cancer tissues compared to those in normal breast tissues." (PMID 38595825, 2024). "Furthermore they also reported that ATRA treatment reduced S100A10 expression but not ANXA2 mRNA or protein levels in the MCF-7 breast cancer cells." (PMID 30621740, 2019). "ATRA treatment in MCF-7 breast cancer cells reduce S100A10 but not annexin A2 transcript and protein levels, indicating that ATRA can regulate S100A10 levels independently of PML/RARα and annexin A2." (PMID 30572596, 2018).
gastric cancer (33 papers, 2002 to 2025). A primary or metastatic malignant neoplasm involving the stomach. "For example, elevated levels of S100A10 have been reported to be associated with several types of cancer, including colorectal cancer, basal-type breast cancer, lung cancer, gastric cancer and pancreatic ductal cancer." (PMID 31739800, 2019). "S100A10 is overexpressed in gastric cancers, precancerous lesions in the stomach, and high S100A10 expression is associated with gastric cancer metastasis to the lymph nodes." (PMID 30572596, 2018). "S100A10 is overexpressed in gastric cancer and is essential for tumour-associated macrophage migration into tumour sites." (PMID 25079072, 2014). "Succinylation at K47 reduces S100A10 from its ubiquitination and proteasomal degradation and allows for plasminogen activation and gastric cancer cells to migrate and invade the gastric cancer cells." (PMID 40865948, 2025). "Specifically, CPT1A promotes the succinylation of S100A10, enhancing the invasive ability of human gastric cancer." (PMID 40070041, 2025). "Li et al21 elaborated that S100A10 is markedly upregulated in gastric cancer and activates the mTOR pathway by interacting with annexin A2 to accelerate tumor glycolysis, thereby promoting malignant cell proliferation while suppressing apoptosis." (PMID 39128058, 2024). "S100A10 has been shown to increase the malignant growth of cancer cells by activating the mTOR signaling pathway in osteosarcoma, gastric cancer, pancreatic ductal adenocarcinoma (PDAC), and HCC." (PMID 37892132, 2023). "CPT1A succinylated S100A10 at lysine 47, and the degree of succinylation was elevated in human gastric cancer." (PMID 37033619, 2023). "For example, S100A10 promotes hepatocellular carcinoma, gastric cancer, and osteosarcoma cell proliferation and suppresses apoptosis via enhanced aerobic glycolysis through mTOR signaling." (PMID 37892132, 2023). "CPT1A can modulate the succinylation of enolase 1 to enhance the growth of breast cancer and the succinylation of S100A10 to facilitate the spread of gastric cancer." (PMID 37033619, 2023). "In gastric cancer, the calcium-binding cytosolic protein S100A10 is overexpressed and is essential for the invasion and migration of tumor cells." (PMID 37033619, 2023). "ANXA2 interacts with S100A10 in gastric cancer to activate the mTOR pathway and inhibit apoptosis in gastric cancer cells." (PMID 37420211, 2023). "SIRT5 regulates desuccinylation, and the levels of succinylated S100A10 were increased in human gastric cancer." (PMID 35278714, 2023). "S100A10 was highly expressed in gastric cancer compared with normal gastric mucosa tissues, which was involved in the occurrence and development of gastric cancer." (PMID 35342420, 2022). "Previous studies reported that S100A10 accumulation was involved in gastric cancer cell invasion and migration through the succinyltransferase CPT1A and SIRT5-mediated desuccinylation." (PMID 34178044, 2021). "The results illustrated a higher rate of lysine succinylation of S100A10 in gastric cancer than in normal samples." (PMID 34944416, 2021). "Together, these results suggest a role of S100A10 in gastric cancer by promoting aerobic respiration via the mTOR signaling pathway." (PMID 34944416, 2021). "Kaplan–Meier results demonstrated a significant association between high expression of S100A10 and low survival, which illustrates the potential value of S100A10 as a prognostic tool for patients with gastric cancer." (PMID 34944416, 2021). "Of these, S100A2 has been implicated in CRC as a prognostic marker, and S100A10, itself a biomarker in CRC was shown to play a pivotal role in gastric cancer invasion." (PMID 34233735, 2021). "In the last two decades, there have been multiple studies demonstrating the potential of S100A10 as a biomarker in gastric cancer." (PMID 34944416, 2021).